HOXA9 (homeobox A9)
Description:
Sequence-specific transcription factor which is part of a developmental regulatory system that provides cells with specific positional identities on the anterior-posterior axis. Required for induction of SELE/E-selectin and VCAM1 on the endothelial cells surface at sites of inflammation. Positively regulates EIF4E-mediated mRNA nuclear export and also increases the translation efficiency of ODC mRNA in the cytoplasm by competing with factors which repress EIF4E activity such as PRH (By similarity).
Synonyms: HOX1G; ABD-B; HOX1; HOX1.7
Tractability: PROTAC: ubiquitination databases record sites on it.
Gene: Protein-coding gene on chromosome 7 (27,162,438 to 27,175,180, reverse strand). Ensembl gene ENSG00000078399.
Subcellular location: Nucleus; Cytoplasm
Subcellular location (Human Protein Atlas): Nucleoplasm
Gene Ontology:
Molecular function: enzyme binding; protein binding; sequence-specific double-stranded DNA binding; DNA-binding transcription factor activity; DNA-binding transcription factor activity, RNA polymerase II-specific; RNA polymerase II cis-regulatory region sequence-specific DNA binding; DNA binding; DNA-binding transcription activator activity, RNA polymerase II-specific
Biological process: endothelial cell activation; anterior/posterior pattern specification; embryonic skeletal system morphogenesis; negative regulation of myeloid cell differentiation; proximal/distal pattern formation; regulation of transcription by RNA polymerase II; DNA-templated transcription; positive regulation of transcription by RNA polymerase II; prostate gland development; regulation of DNA-templated transcription; response to testosterone
Cellular component: cytoplasm; nucleoplasm; nucleus; chromatin; transcription regulator complex
Genetic constraint (gnomAD): Loss-of-function variants: 18 observed, 18.62 expected, observed/expected ratio (o/e) 0.97, 90% interval 0.67 to 1.43. The upper end of that interval is the gene's LOEUF score, 1.43, which puts it in group 5 of 6, group 1 being the genes least tolerant of losing a copy. Missense variants: 443 observed, 367.16 expected, observed/expected ratio (o/e) 1.21, 90% interval 1.12 to 1.3. Synonymous variants: 198 observed, 161.75 expected, observed/expected ratio (o/e) 1.22, 90% interval 1.09 to 1.38.
Homologues: Orthologues: chimpanzee HOXA9 (99% identical), macaque HOXA9 (99% identical), mouse Hoxa9 (98% identical), pig HOXA9 (98% identical), dog HOXA9 (97% identical), rabbit HOXA9 (96% identical), guinea pig HOXA9 (96% identical), rat Hoxa9 (75% identical), tropical clawed frog soho1 (15% identical), zebrafish hmx4 (15% identical). Paralogues in human: HMX3 (21% identical), HMX1 (19% identical), HMX2 (19% identical).
Diseases named in the same sentence as HOXA9 in open-access papers:
HOXA9 is named in the same sentence as 140 diseases in open-access papers, as found by Europe PMC text mining. Sharing a sentence is not in itself a finding about the gene and the disease. The quoted sentences say what the papers report.
leukemia (241 papers, 2004 to 2026). A malignant (clonal) hematologic disorder, involving hematopoietic stem cells and characterized by the presence of primitive or atypical myeloid or lymphoid cells in the bone marrow and the blood. "In fact, analysis of HoxA9 and MEIS1 gene expression in children with leukemia confirmed the association of both HoxA9 and MEIS1 overexpression in different leukemia subtypes including acute myeloid leukemia (AML) and mixed lineage leukemia (MLL)." (PMID 41535654, 2026). "Acute myeloid leukemia (AML) is commonly linked to heightened expression of HOXA9, which stimulates the development of leukemia by activating particular enhancers, including super enhancers, in leukemia cells." (PMID 39838405, 2025). "In leukemia and solid tumors, HOXA9 has been specifically linked to the invasiveness and proliferation of cancer cells, which promotes the advancement of the disease and resistance to treatment." (PMID 41155227, 2025). "Leukemia subtypes with hallmark overexpression of HOXA9 include but are not limited to those carrying KMT2A gene rearrangements (KMT2A-r), NPM1c mutations, NUP98-translocations, and EZH2 mutation." (PMID 38216972, 2024). "Although previous studies have demonstrated that RNA-binding proteins (RBPs) were frequently mutated in AML patients and essential for leukemia growth, how RBPs genes regulate HOXA9 expression and AML survival remains uncharacterized." (PMID 38216972, 2024). "Accumulating genetic evidence also indicates that HOXA9 dysregulation is sufficient and necessary for leukemic transformation, and loss of function of HOXA9 and downstream pathways consequently impaired leukemia maintenance." (PMID 38216972, 2024). "Aberrant high expression of HOXA9 is a hallmark of MLL-r leukemia, including AML and ALL, and is associated with a poor prognosis for this disease." (PMID 38016946, 2023). "For example, USF2 was associated with progression of leukemia through upregulation of HOXA9, but disruption of USF1 alone had minimal effects." (PMID 37515158, 2023). "Re-expression of HoxA9 in Llgl1-deficient leukemic cells resulted in a complete phenotypic rescue and resulted in lethal leukemia with 100% penetrance (median survival 56 days)." (PMID 37587260, 2023). "Recent studies have identified DHODH as a therapeutic target for AML, and DHODH inhibitors cause myeloid differentiation and show potent anti-leukaemia effects in several AML mouse models including the Hoxa9/Meis1 model." (PMID 36285442, 2022). "Another study has discovered cooperation of NPM1 and IDH2 mutations for leukemia development in mice through activation of the Hoxa9/Meis1 pathway, where NPMc and IDH2/R140Q increase the expression of Hoxa9 and Meis1, respectively." (PMID 34944812, 2021). "Gene expression annotation revealed distinct distributions of cells expressing leukemia-associated genes (Meis1, Hoxa9, and Myc; clustered toward the right) vs. myeloid-differentiation markers (Cd11b, Gr1, and Ltf; clustered toward the left)." (PMID 34210975, 2021). "Co-expression of HOXA9 with MEIS1 causes leukemia in mice which recapitulates MLL fusion-mediated leukemia." (PMID 34310280, 2021). "In HSCs, cohesin RAD21 depletion was found to reduce the PcG-associated repressive H3K27me3 mark and cause de-repression of PcG target genes, particularly at leukemia-associated HoxA7 and HoxA9, consequently enhancing self-renewal." (PMID 34202641, 2021). "The persistent expression of the posterior HOXA cluster, often in particular HOXA9, in N98-related leukemia is thought to be a major cause for the arrested terminal differentiation of myeloid precursor cells (for review see:)." (PMID 34831074, 2021). "Somewhat surprisingly, the list of target promoters failed to include most MLL-AF9 ChIP targets with the leukemia self-renewal associated Hox gene signature, namely Hoxa9, Hoxa10 and Meis1, escaping Kat2a-dependent promoter acetylation control." (PMID 31985402, 2020).
leukemia (continued). "Collectively, these efforts would clarify the molecular mechanisms underlying aberrant HOXA9 activation in leukemias, thus providing the foundation to develop clinically relevant therapies to target the expression and/or function of HOXA9 in leukemia patients." (PMID 33001025, 2020). "The histone demethylase JMJD1C is overexpressed in patients with myeloproliferative neoplasms (MPNs) and has been implicated in leukemic stem cell function of MLL-AF9 and HOXA9-driven leukemia." (PMID 32017785, 2020). "Overall, the expression of Meis1–3, Pbx1–3, and their associated partner, Hoxa9, were observed as upregulated in thymoma, pancreatic adenocarcinoma, glioblastoma, glioma, lymphoma, and leukemia when compared to corresponding healthy adult tissues." (PMID 33402862, 2020). "At the level of epigenetically modified DNA, different mutations of the DNA methyl transferase protein DNMT3A are associated with modifications of the DNA methylation status, leading to a leukemia associated with HOXA9/MEIS1 expression." (PMID 31213012, 2019). "HOXA9 (Homeobox A9) is a homeotic transcription factor known for more than two decades to be associated with leukemia." (PMID 31213012, 2019). "HOXA7 and HOXA9 appear to be required for efficient in vitro myeloid immortalization via the replacement of leukemia-associated fusion proteins with MLL fusion proteins." (PMID 31426381, 2019). "This aberrant epigenetic event dysregulates the expression of many MLL target genes, such as HoxA9, HoxA7, and Meis1 whose overexpression can cause leukemia." (PMID 27316347, 2016). "This aberrant histone methylation at the MLL target gene loci causes overexpression of many Hox genes (e.g., HoxA7, HoxA9, and Meis1) that eventually cause leukemia initiation." (PMID 26970896, 2016). "We and others have previously shown that Hoxa9 and Meis1 act in synergy to cause leukemia in transplantation models." (PMID 27525194, 2015). "Methylation of HOXA9 has been reported previously in oral cavity cancer, and methylation and loss of expression of HOXA9 reported in breast, lung, ovarian and bladder cancer, whereas HOXA9 is well known to act as an oncogene in leukemia." (PMID 24886209, 2014). "HoxA9 and HoxA10 are increased in cells expressing Mll-Ell, a leukemia-associated MLL1 fusion protein." (PMID 25531430, 2014). "Leukemia-associated, constitutively active mutants of Shp2 block cytokine-induced tyrosine phosphorylation of HoxA9 and HoxA10." (PMID 25531430, 2014). "Deregulated expression of Hox genes such as HoxA9 is associated with development of myeloproliferative disorders and leukemia and indicates a poor prognosis." (PMID 24177192, 2013). "Among the upregulated probesets were two homeobox genes, HOXC6, a transcription factor expressed in the developing skeleton, and HOXA9, a transcription factor involved in myeloid differentiation linked with increased cell proliferation in leukaemia." (PMID 24148222, 2013). "In bone marrow transformation assays and mouse model systems, co-expression of Meis1 and HoxA9 together cause aggressive leukemias in mice and together can replace the requirement for an active MLL-ENL fusion protein." (PMID 24213472, 2012). "HOXA9 overexpression has long been thought to be a hallmark of MLL-FP leukemias and many human patient samples are dependent on overexpression of HOXA9 for their continued growth and leukemic potential." (PMID 24213472, 2012). "Two probes for MEIS1 gene (204969_at, 15559477_s_at), which encodes a cofactor for HOX proteins that can accelerate Hoxa9-dependent leukemia, were shown to be strongly expressed in MLL positive samples, as previously reported." (PMID 19549311, 2009). "This process speeds up the development of leukemia caused by HOXA9." (PMID 39838405, 2025). "Moreover, KDM3C is required for self-renewal in leukemia, as it functions with aberrantly expressed self-renewal-associated genes, such as homeobox A9 (HOXA9)." (PMID 38926399, 2024).
leukemia (continued). "Ectopic expression of HOXA9 rescues impaired leukemia cell proliferation upon RBM5 loss." (PMID 38216972, 2024). "Thus, certain MLL target genes, such as HoxA9 and Myc, are constitutively or excessively expressed, causing leukemia." (PMID 37958457, 2023). "Moreover, dysregulation of MLL1 leads to constitutive or over-expression of certain Hox genes (e.g., HoxA9), which has been found to cause leukemia." (PMID 33823889, 2021). "The increased expression of HOXA9 could be found in most aggressive leukemia, and HOXA13 physically linked to tumor growth and angiogenesis." (PMID 34606634, 2021). "Ectopic expression of Hoxa9 rescued impaired leukemia cell proliferation upon USF2 loss." (PMID 33001025, 2020). "MiR-196b directly targets HOXA9, whose overexpression is associated with bad prognosis in leukemia." (PMID 31379917, 2019). "Indeed, in leading-edge analyses, there was a highly significant association of higher IRX3 expression in human HOXA9+ AML with greater repression of IRX3-repressed genes identified in murine leukemias." (PMID 29346763, 2018). "Interestingly, leukemia-associated pathways that were regulated by ERG in murine fetal liver-derived HSPCs (Hoxa9-Meis1, CBFA2T3, and repression of myeloid differentiation genes) were ranked at the leading edge of gene sets that were significantly perturbed after HDAC3 inhibition." (PMID 37735473, 2023). "However, the CBL0137/panobinostat combination did not induce significant changes in the levels of acetylation or methylation of specific histones associated with KMT2A-r leukemia or in the expression levels of leukemogenic KMT2A target genes such as HOXA9 and MEIS1 before induction of apoptosis." (PMID 35677155, 2022). "Furthermore, we found that the imputed H3K27me3 scores also formed inverse patterns of gene association from H3K4me3, where genes such as HOXA9 that were rarely marked by H3K4me3 in 1° MPAL-1 leukemia cells showed elevated H3K27me3 scores in the majority of tumor cells (~55%)." (PMID 34663924, 2021). "Experimental interference with the dimerisation between PBX3 and MEIS1 resulted in destabilisation of MEIS1 and a significant decline in HoxA9-induced proliferation and colony formation in primary cells and animal models of leukemia." (PMID 41535654, 2026). "EPZ-5676 downregulates HOXA9/PBX3 expression and induces apoptosis in NPM1-mutated leukemia cells, establishing its therapeutic potential for MLL-r leukemias." (PMID 41199817, 2025). "RNA-seq analysis of A485-treated K/C-III leukemia cells further revealed significant downregulation of key hematopoietic factors, including Hoxa9, Hoxa10, Meis1, Cd34, c-Kit, and Csf1r." (PMID 40830799, 2025). "Experimental mouse models reveal that high-level expression of BCR::ABL alone is insufficient to induce leukemia, whereas co-expression with Setbp1, Hoxa10 or Hoxa9 produces aggressive leukemia within 3 weeks." (PMID 41179655, 2025). "In connection with these data, KMT2A::AFF1 fusion protein promotes leukemia progression mainly by activating pro-leukemogenic factors HOXA9 and MEIS1." (PMID 40722046, 2025). "The association of oncogenic KMT2A-fusion proteins with Menin and LEDGF is required for its chromatin binding, target gene expression such as the HOXA9 and MEIS1, and implicated the Menin-KMT2A interaction as a therapeutic opportunity in these leukemias." (PMID 40374809, 2025). "PRMT1’s interaction with β-Catenin and HOXA9 in LSK-MLL-ENL cells plays a crucial role in mediating leukemia self-renewal, highlighting the significance of the HOXA9/PRMT1 molecular network beyond β-Catenin dependence." (PMID 38326807, 2024). "HOXA9 plays a key role in KMT2A-rearranged (KMT2A-r) leukemia, mediated by binding of the KMT2A fusion protein to HOX gene promoters and recruitment of DOT1L H3K79 methyltransferases." (PMID 38601080, 2024).
leukemia (continued). "HOXA9, an oncogenic driver in leukemia, is regulated in multiple levels, including transcriptional, posttranscriptional, and translational levels via numerous known regulators." (PMID 38216972, 2024). "Previously, we had successfully established two KMT2A-r leukemia cell lines with the P2A-mCherry cassette insertion into endogenous HOXA9 locus and fully recapitulated the endogenous gene expression." (PMID 38216972, 2024). "DOT1L stabilized by glucose metabolism was found to regulate the expression of homeobox A9 (HOXA9) and meis homeobox 1 (MEIS), an effect associated with the proliferation of MLL-fusion leukemia." (PMID 39394462, 2024). "HOXA9 also suppresses apoptotic/differentiation factors, promoting leukemia cell survival and maintaining a more stem-like state." (PMID 38601080, 2024). "The two most important aberrantly expressed genes in KMT2A-rearranged leukemias are HOXA9 and MEIS1 since their upregulation was shown to be crucial for leukemogenesis." (PMID 39834944, 2024). "In contrast, the overexpression of HOXA genes, particularly HOXA9, has been observed concurrently with JAK3 GOF mutations in T-ALL with HOXA9 overexpression co-operating with the JAK3 M511I mutation to elicit a short latency, aggressive leukemia in mice." (PMID 38474223, 2024). "The oncogenic protein HOXA9 plays a critical role in leukemia transformation and maintenance, and its aberrant expression is a hallmark of most aggressive acute leukemia." (PMID 38216972, 2024). "LD on marrow extracted 8 weeks post-transplantation showed an approximately 5-fold greater frequency of leukemia initiating cells (LICs) in cKO+Hoxa9 marrow." (PMID 39004675, 2024). "In instances of human leukemia, recurrent chromosomal translocations give rise to an aberrant chimeric cancer variant featuring NUP98 and HOXA9 proteins." (PMID 38383403, 2024). "We have previously established a state-of-art cellular tool by inserting the mCherry reporter cassette into endogenous HOXA9 locus in KMT2A-r OCIAML2 and SEM leukemia cell lines, allowing for unbiased genome-wide screening to reveal HOXA9’s regulators." (PMID 38216972, 2024). "In this work, we use a CRISPR-mediated loss-of-function screen against HOXA9-bound peaks identified by ChIP-seq to systematically evaluate HOXA9-bound cis-regulatory elements in MLL-r leukemia cell models." (PMID 38016946, 2023). "Taken together, these extensive efforts will undoubtedly improve our understanding of how HOXA9 works in MLL-r leukemia maintenance and provide insights for alternative targeting and therapeutic innovation." (PMID 38016946, 2023). "SW2_110A displayed anti-proliferative effects in MLL-AF9 leukemia cells and demonstrated that the CBX8 chromodomain is required for CBX8-mediated HOXA9 gene activation in MLL-AF9 leukemia." (PMID 36948085, 2023). "HOXA9 is upregulated in leukemia but downregulated in breast cancer, where it acts as a tumor suppressor by regulating BRCA1 expression." (PMID 38203393, 2023). "Conversely, re-expression of HoxA9 can rescue this phenotype and results in re-establishment of an immature and aggressive leukemia." (PMID 37587260, 2023). "ChIP–seq profiling of Stat5a, Runx1 and Runx2 confirmed the motif analysis, demonstrating cobinding of these transcription factors and BAF or MLL1 and MLL4 complexes at key pro-leukemia genes including Hoxa7 and Hoxa9." (PMID 37580596, 2023). "Despite the absence of a unique transcriptional regulator for SCUBE1, recent research has shown that in MLL-r leukemia, homeobox A9 (HOXA9) and Meis homeobox 1 (MEIS1) act together to upregulate SCUBE1." (PMID 37237303, 2023). "We identified a series of HOXA9-driven cis-regulatory elements that are critical for the survival of MLL-r leukemia cells, including h-FLT3, a distal enhancer critical for the high expression of FLT3 in MLL-r leukemia and its survival." (PMID 38016946, 2023). "HOXA9 induces breast cancer and leukemia, and HOXA10 is an oncogene of prostate and testicular cancers." (PMID 37834206, 2023).